MAGED1 (MAGE family member D1)
Diseases named in the same sentence as MAGED1 in open-access papers:
MAGED1 is named in the same sentence as 42 diseases in open-access papers, as found by Europe PMC text mining. Sharing a sentence is not in itself a finding about the gene and the disease. The quoted sentences say what the papers report.
breast carcinoma (6 papers, 2012 to 2021). "It was reported that the expression of MAGED1 was down-regulated in breast carcinoma cell lines and in glioma stem cells." (PMID 22935435, 2012). "Studies have also implicated CPNE8, MAGED1, and RNF144A in ovarian and breast cancers." (PMID 32849822, 2020). "The down-regulation of MAGED1 expression has been shown in breast carcinoma cell lines and in glioma stem cells and may play an important role in apoptosis and anti-tumorigenesis." (PMID 22935435, 2012).
melanoma (5 papers, 2010 to 2025). A malignant, usually aggressive tumor composed of atypical, neoplastic melanocytes. "Another interesting category is that of circadian rhythm, whose biology frequently involves translational control for temporal expression patterns, such as melanoma antigen-encoding gene D1 (Maged1) and inhibitor of DNA binding 1 (Id1)." (PMID 33472078, 2021). "NRAGE, a neurotrophin-receptor-interacting melanoma antigen-encoding gene homolog, also known as MAGED1 or Dlxin-1, was discovered as a new member of the melanoma antigen family and encodes a cancer-related protein." (PMID 35433476, 2022). "Notably, the melanoma antigen MAGED1, which also displays hyperacetylated sites upon HDAC3 deletion/inactivation, plays a major role in apoptosis and cell cycle arrest, which could provide a further link between HDAC3 function and the reduced viability of HDAC3 CI or HDAC3 KO clones." (PMID 35994477, 2022).
pulmonary hypertension (5 papers, 2021 to 2024). Increased pressure within the pulmonary circulation due to lung or heart disorder. "Notably, YTHDF1 knockdown attenuated ameliorated pulmonary artery smooth muscle cell proliferation, phenotypic switching, and the development of pulmonary hypertension by enhancing MAGED1 translation both in vivo and in vitro." (PMID 38509077, 2024). "YTHDF1 was reported to regulate pulmonary hypertension through the control of MAGED1." (PMID 36911406, 2023). "It has been shown that YTHDF1 was up-regulated in human and rodent pulmonary hypertension samples, knockdown of YTHDF1 ameliorated PASMC proliferation, phenotypic switching, and pulmonary hypertension development via promoting the translation of MAGED1 both in vivo and in vitro." (PMID 36650570, 2023).
depression (4 papers, 2012 to 2025). "Loss of Maged1 in mice has been linked to depression, cognitive disorder, and drug addiction." (PMID 36774489, 2023). "More importantly, Maged1 regulates a large variety of behaviors and has been implicated in psychiatric disorders, including regulation of circadian rhythms, social behavior, depression, memory formation and cocaine addiction." (PMID 36774489, 2023). "Limited researches have reported that Maged1 knocked mice-displayed depression-like behaviors by serotonin transporter (SERT) ubiquitylation." (PMID 34220431, 2021). "We infer that Maged1 plays an important role in depression through effecting the 5-HT systems." (PMID 34220431, 2021).
Obesity (4 papers, 2012 to 2022). Accumulation of substantial excess body fat. "Another subsequent animal study observed a similar phenomenon in which MAGED1-deficient mice showed late-onset obesity, owing to reduced energy expenditure and physical activities." (PMID 35213968, 2022). "One study concluded that MAGED1-deficient mice showed hyperphagia and reduced motor activity, which led to the development of obesity." (PMID 35213968, 2022). "Loss of MAGED1 leads to reduced social interactions, a behavioral phenotype that resemble autism, late onset obesity, and hyperphagia." (PMID 32708109, 2020). "MAGED1-deficient mice develop progressive obesity associated with hyperphagia and reduced motor activity." (PMID 28414775, 2017). "Maged1 is a transcriptional co-activator that has been implicated in the regulation of myogenic differentiation, sexual behavior, obesity and the transcriptional function of Dlx5, a positive regulator of osteoblast differentiation and bone mass." (PMID 23300464, 2012). "Loss of MAGED1 resulted also in mild obesity, hyperphagia, and hypoactivity, although no study so far investigated muscle tone." (PMID 32708109, 2020). "Maged1 is a transcriptional co-activator involved in a wide-array of cellular processes such as the regulation of myogenic differentiation, circadian rhythms, sexual behavior and obesity, to name a few." (PMID 23300464, 2012).
glioma (3 papers, 2012 to 2020). A benign or malignant brain and spinal cord tumor that arises from glial cells (astrocytes, oligodendrocytes, ependymal cells). "Interestingly, Oncomine analysis revealed that in glioma, several MAGE genes, including MAGED1, MAGED4, and MAGED4B exhibited elevated expression." (PMID 33425727, 2020). "In agreement to this, our analysis revealed that while MAGED1, which is co-expressed with MAGED4, was associated with poor prognosis in glioma, it did not emerge as an independent prognostic factor in multivariate analysis." (PMID 33425727, 2020).
pancreatic cancer (3 papers, 2017 to 2025). "CDK4/6-E2F1 mediates an increase in MAGED1 expression, which promotes FBP1 degradation and the Warburg effect in pancreatic cancer." (PMID 40307228, 2025).
autism (2 papers, 2017 to 2020). Persistent deficits in social interaction and communication and interaction as well as a markedly restricted repertoire of activity and interest as well as repetitive patterns of behavior. "So, MAGED1 is required for Oxt processing or stability, and in human, MAGED1 is involved in autism etiology or cause a neurodevelopmental condition similar to PWS." (PMID 32708109, 2020). "They concluded that a lack of MAGED1 function could play a role in autism." (PMID 28414775, 2017).
cocaine addiction (2 papers, 2023). "Indeed, SNP mutations in USP7 and MAGED1 among polydrug users were associated with varying scores of aggressiveness during cocaine use and a modified transition time to cocaine addiction, respectively." (PMID 38123574, 2023). "Furthermore, we uncover genetic variations in MAGED1 and USP7 associated with altered susceptibility to cocaine addiction and to cocaine-induced aggressive behavior in human subjects." (PMID 38123574, 2023). "Additionally, genetic variations in MAGED1 and USP7 are linked to altered susceptibility to cocaine addiction and cocaine-associated symptoms in humans." (PMID 38123574, 2023). "To assess the potential contributions of MAGED1 and USP7 to CUD directly in humans, we conducted a within-case MAGED1 and USP7 gene analysis with 351 consecutively recruited outpatients with cocaine addiction and genetically verified Caucasian ancestry." (PMID 38123574, 2023).
colorectal cancer (1 paper, 2012). A primary or metastatic malignant neoplasm that affects the colon or rectum. "The expression of MAGED1 in colorectal cancer was significantly correlated with patients’ survival time (p <0.001)." (PMID 22935435, 2012). "In the present study, we demonstrated that MAGED1 also has a close relationship with the clinical features of colorectal cancer, with higher MAGED1 expression in CRC patients correlating with better survival and vice versa." (PMID 22935435, 2012). "MAGED1 protein expression was evaluated by immunohistochemistry in 285 paraffin-embedded, archival primary colorectal cancer tissues." (PMID 22935435, 2012). "According to the definition, the rate of low MAGED1 expression (74/131, 56.5%) in colorectal cancer samples significantly differed from the rate in matched ANT samples (13/131, 10.0%) (p = 0.031)." (PMID 22935435, 2012). "In this study, we investigated MAGED1 expression and its clinical significance in human colorectal cancer." (PMID 22935435, 2012). "According to the scoring system, low MAGED1 expression was detected in 161/285 (56.5%) colorectal carcinomas, while the high MAGED1 expression was detected in 124/285 (43.5%)." (PMID 22935435, 2012). "This is the first study to analyze the prognostic relevance of the MAGED1 expression in colorectal carcinoma." (PMID 22935435, 2012). "Furthermore, MAGED1 expression was down-regulated in 58.8% (77/131) and up-regulated only in 22.1% (29/131) colorectal cancer tissues, compared with their paired ANT tissues according to the scoring system." (PMID 22935435, 2012). "In addition, we analyzed MAGED1 expression in 285 clinicopathologically characterized colorectal cancer patients." (PMID 22935435, 2012). "We found that MAGED1 expression was significantly down-regulated in colorectal cancer tissues compared with their adjacent non-tumorous tissues (ANT) and was associated with the clinical features of colorectal cancer." (PMID 22935435, 2012). "MAGED1 expression was significantly correlated with overall survival in colorectal cancer patients." (PMID 22935435, 2012). "MAGED1 may serve as a novel prognostic biomarker of human colorectal cancer." (PMID 22935435, 2012). "Furthermore, MAGED1 expression was an independent prognostic factor, suggesting that MAGED1 may be a prognostic factor for survival in colorectal cancer patients." (PMID 22935435, 2012). "Furthermore, univariate and multivariate analyses indicated that clinical stage, pathologic differentiation, and MAGED1 expression were independent prognostic factors, suggesting that MAGED1 may be a prognostic factor for survival in colorectal cancer patients." (PMID 22935435, 2012). "In the present study, 131 CRC patients were enrolled to compare their MAGED1 expression between colorectal cancer tissues and paired adjacent non-tumorous tissues." (PMID 22935435, 2012). "In the present study, we demonstrated that MAGED1 expression was down-regulated at both the mRNA and protein levels in colorectal cancer tissues compared to matched adjacent non-tumorous tissues." (PMID 22935435, 2012). "We examined the expression of MAGED1 by qPCR in colorectal cancer tissues and their adjacent non-tumorous tissues taken from 6 cases and performed Western blotting and IHC analyses." (PMID 22935435, 2012). "Although MAGED1 may play an important role in apoptosis and anti-tumorigenesis, there are no reports on its clinical role in colorectal cancer." (PMID 22935435, 2012). "In the present study, we found that MAGED1 expression was significantly down-regulated in colorectal cancer tissues compared with adjacent non-tumorous tissues and was associated with clinical stage, T classification, N classification, M classification and pathologic differentiation." (PMID 22935435, 2012).
colorectal cancer (continued). "Thus, the further study including overexpression and knockdown of MAGED1 expression in CRC cells will be needed to explore the mechanism by which MAGED1 is involved in the development and progression of colorectal cancer and its exact regulating pathway in vitro and in vivo." (PMID 22935435, 2012).
colorectal mucinous adenocarcinoma (1 paper, 2012). An invasive colorectal adenocarcinoma characterized by the presence of extracellular mucin pools that contain malignant glandular epithelial structures. "In addition, most of the colorectal mucinous adenocarcinoma cases (12/17) were demonstrated low MAGED1 expression." (PMID 22935435, 2012). "MAGED1 protein was detected in 261 of 285 CRC cases (91.6%), but in only 5 of 17 colorectal mucinous adenocarcinoma cases (29.4%)." (PMID 22935435, 2012).
dengue (1 paper, 2019). "Previous study has found that during the acute phase of dengue, the expression level of MAGED1 was greater in DHF patients compared to DF patients." (PMID 30868055, 2019). "Interestingly, in patients of dengue and the acute DHF patients, the pro‐apoptotic PDRX4 and MAGED1 genes were over‐expressed." (PMID 30868055, 2019).
developmental delay (1 paper, 2017). "Loss of GSPT2 and/or MAGED1 function may contribute to the intellectual disability and developmental delay seen in males with these deletions." (PMID 28414775, 2017).
Duchenne muscular dystrophy (1 paper, 2010). Duchenne muscular dystrophy (DMD) is a neuromuscular disease characterized by rapidly progressive muscle weakness and wasting due to degeneration of skeletal, smooth and cardiac muscle. "Interestingly, data obtained by high throughput expression analysis indicate that the expression of MAGED1 RNA is upregulated in the muscles of Duchenne muscular dystrophy (DMD) patients, a condition in which muscle regeneration concomitantly occurs with the degeneration of myofibers." (PMID 20646279, 2010).
Intellectual disability (1 paper, 2017). "Changes in MAGED1 have not been associated with intellectual disability in humans, but loss of MAGED1 function is associated with neurocognitive and neurobehavioral phenotypes in mice." (PMID 28414775, 2017).
malignant mesothelioma (1 paper, 2020). A malignant neoplasm of the pleura or peritoneum, arising from mesothelial cells. "Using whole exome sequencing of five WDPMs of the peritoneum, we have identified distinct mutations in EHD1, ATM, FBXO10, SH2D2A, CDH5, MAGED1, and TP73 shared by WDPM cases but not reported in malignant mesotheliomas." (PMID 32545767, 2020).
mucinous adenocarcinoma (1 paper, 2012). An invasive adenocarcinoma composed of malignant glandular cells which contain intracytoplasmic mucin. "We found that MAGED1 expression was low in most of the mucinous adenocarcinomas of CRC (12/17)." (PMID 22935435, 2012). "However, because we could only obtain a small number of mucinous adenocarcinoma samples, we were unable to demonstrate a significant correlation between the MAGED1 expression and the histological types in CRC (p = 0.227)." (PMID 22935435, 2012). "Conversely, the rate of low MAGED1 expression (148/268) in non-mucinous adenocarcinoma did not significantly differ from the rate of high expression (120/268)." (PMID 22935435, 2012).
neuroblastoma (1 paper, 2023). Neuroblastoma (NB) is the most common solid, extracranial childhood tumor. "To test whether MAGED1 associates with USP7 in human cells, we performed co-IP-MS of MAGED1 in two different human cell lines: human embryonic kidney 293 T (HEK293T) and neuroblastoma (SH-SY5Y) cells." (PMID 38123574, 2023).
Parkinson disease (1 paper, 2023). A progressive degenerative disorder of the central nervous system characterized by loss of dopamine producing neurons in the substantia nigra and the presence of Lewy bodies in the substantia nigra and locus coeruleus. "However, the role of Maged1 in Parkinson’s disease (PD) remains unclear." (PMID 36774489, 2023).
peritoneal mesothelioma (1 paper, 2020). A benign or malignant mesothelial neoplasm that arises from the peritoneum. "Notably, we found WDPM specific mutations in EHD1, FBXO10, CHD5, MAGED1, ATM, and TP73 genes that were absent in peritoneal mesothelioma." (PMID 32545767, 2020).
teratoma (1 paper, 2023). A non-seminomatous germ cell tumor characterized by the presence of various tissues which correspond to the different germinal layers (endoderm, mesoderm, and ectoderm). "Equally important, Park and colleagues reported that the knockdown of melanoma-associated antigen D1 (Maged1) causes an increase in ectodermal differentiation and reduction in ERK1/2 phosphorylation, cell cycle progression, and teratoma formation in nude mice." (PMID 37176093, 2023).
toxoplasmosis (1 paper, 2019). A parasitic disease contracted by the ingestion or fetal transmission of toxoplasma gondii. "In the KEGG results, we found that DF‐related genes, STAT1 and IL12A, were enriched in the signaling pathway of ‘toxoplasmosis’, and MAGED1 was enriched in ‘protein processing in endoplasmic reticulum’." (PMID 30868055, 2019).
tumor (14 papers, 2011 to 2026). "In the univariate analysis for LGG, we used MAGEH1 expression, MAGED1 expression, age, gender, tumor histology, WHO grade, IDH mutation status, 1p/19q codeletion status, and MGMT promoter methylation status to analyze the association of these variables to patient outcome." (PMID 33425727, 2020). "Among the primary tumor samples, AKAP9, KDM2B, MAGED1, MKI67, PCLO, and TRAF1 mutations were identified." (PMID 41614915, 2026). "Among the 95 primary tumor samples, AKAP9, KDM2B, MAGED1, MKI67, PCLO, and TRAF1 mutations were identified as single-occurrence events and were absent in the metastatic samples." (PMID 41614915, 2026). "Moreover, primary tumor samples had exclusive mutations in AKAP9, KDM2B, MAGED1, MKI67, PCLO, and TRAF1." (PMID 41614915, 2026). "Unlike the type I MAGE genes, which encode tumor antigens, MAGED1 encodes a protein involved in the apoptosis pathway." (PMID 22935435, 2012). "Given the number of mutations and the nature of the mutations found, including at least one tumor suppressor gene, TP73, and several genes that may be associated with other types of malignancy (ATM, CDH5, MAGED1), WDPM clearly appears to be a functionally benign neoplasm and not a reactive process." (PMID 32545767, 2020).
cancer (12 papers, 2011 to 2025). A tumor composed of atypical neoplastic, often pleomorphic cells that invade other tissues. "On the other hand, MAGED1 was linked with cell-death mechanisms, which are often disrupted in cancer." (PMID 30083469, 2018). "Interestingly, these proteins, in addition to other identified HDAC3 targets including MB21D2 and the melanoma-associated antigen MAGED1, also have cancer-associated functions." (PMID 35994477, 2022). "Several of the hits including MAGED1 and KCTD12 have been described in both cancer context and general cellular processes." (PMID 40193385, 2025). "Maged1 belongs to the large MAGE family, also known as NRAGE or Dlxin-1, first described as genes expressed in cancer and germline cells." (PMID 36774489, 2023). "For example, PLEC, ANXA10, EHF, SLC4A, and CUL4A are expressed at high levels in MDA-MB-231 relative to MCF-7 cells, and MAGED1, SYK, and EPCAM are expressed at higher levels in triple-negative cancer tissues relative to non-invasive control tissues." (PMID 26053433, 2015).
MAGED1 also shares sentences with these, for which no sentence is quoted: esophageal cancer (2 papers); gastric cancer (2); Prader-Willi syndrome (2); cocaine use disorder (1); cognitive disorder (1); colon cancer (1); embryonic carcinoma (1); hepatocellular carcinoma (1); male infertility (1); neurodevelopmental disorder (1); non-small cell lung carcinoma (1); osteosarcoma (1); ovarian carcinoma (1); psychiatric disorder (1); Schaaf-Yang syndrome (1); schizophrenia (1); X-linked disease (1); X-linked intellectual disability (1).